SLC24A3 (solute carrier family 24 member 3)
Description:
Calcium, potassium:sodium antiporter that transports 1 Ca(2+) and 1 K(+) in exchange for 4 Na(+).
Synonyms: NCKX3
Tractability: Antibody: UniProt places it where antibodies can reach, with high confidence; its Gene Ontology location is reachable by antibodies, with high confidence; UniProt predicts a signal peptide or a membrane-spanning region.
Gene: Protein-coding gene on chromosome 20 (19,212,510 to 19,722,926, forward strand). Ensembl gene ENSG00000185052.
Subcellular location: Cell membrane
Subcellular location (Human Protein Atlas): Golgi apparatus; Cytosol
Pathways (Reactome):
Transport of small molecules: Sodium/Calcium exchangers
Gene Ontology:
Molecular function: calcium, potassium:sodium antiporter activity; calcium channel activity
Biological process: calcium ion transmembrane transport; intracellular calcium ion homeostasis; potassium ion transmembrane transport; sodium ion transmembrane transport; bone mineralization; negative regulation of gene expression; positive regulation of gene expression; transport across blood-brain barrier; transmembrane transport
Cellular component: cell periphery; plasma membrane; membrane
Genetic constraint (gnomAD): Loss-of-function variants: 20 observed, 67.79 expected, observed/expected ratio (o/e) 0.3, 90% interval 0.21 to 0.43. The upper end of that interval is the gene's LOEUF score, 0.43, which puts it in group 1 of 6, group 1 being the genes least tolerant of losing a copy. Missense variants: 571 observed, 780.35 expected, observed/expected ratio (o/e) 0.73, 90% interval 0.68 to 0.78. Synonymous variants: 322 observed, 306.69 expected, observed/expected ratio (o/e) 1.05, 90% interval 0.96 to 1.15.
Homologues: Orthologues: chimpanzee SLC24A3 (99% identical), macaque SLC24A3 (99% identical), mouse Slc24a3 (97% identical), rat Slc24a3 (96% identical), rabbit SLC24A3 (96% identical), dog SLC24A3 (95% identical), pig SLC24A3 (93% identical), guinea pig SLC24A3 (90% identical), tropical clawed frog slc24a3 (77% identical), zebrafish slc24a3 (67% identical), Drosophila melanogaster zyd (33% identical), Drosophila melanogaster CG17167 (26% identical), and 1 more. Paralogues in human: SLC24A4 (57% identical), SLC24A1 (36% identical), SLC24A2 (34% identical), SLC24A5 (30% identical).
Diseases named in the same sentence as SLC24A3 in open-access papers:
SLC24A3 is named in the same sentence as 53 diseases in open-access papers, as found by Europe PMC text mining. Sharing a sentence is not in itself a finding about the gene and the disease. The quoted sentences say what the papers report.
migraine (11 papers, 2017 to 2025). "A single nucleotide variant in SLC24A3 has been identified as a risk factor for migraine, a common comorbidity in PCS and ME/CFS." (PMID 41050647, 2025). "In our study, substantially elevated SNP-based heritability and replicable top hits in risk loci of PRDM16, FHL5, ASTN2, STAT6/LRP1, SLC24A3 genes were found among migraine-first patients." (PMID 39333847, 2024). "A recent biocomputational genetic association analysis of migraine and RA demonstrated that there is a phylogenetic relationship between the genes responsible for migraine and RA, such as SLC24A3 and HLA-B, MPPED2 and STAT4, and ATP1A2 and IL6R, respectively." (PMID 35281991, 2021). "Unadjusted analyses showed that two SNPs were associated with migraine at a Bonferroni corrected threshold of 0.0013 (0.05/40): rs4814864, located in the SLC24A3 gene (OR = 1.32, p = 0.0008), and rs186166891, located in the SUGCT gene (OR = 1.48, p = 0.0004)." (PMID 28656458, 2017). "Variants in SLC24A3 (NCKX3) have been associated with hypertension and other common cardiovascular diseases as well as migraine and Alzheimer’s disease." (PMID 36614039, 2022).
Hypertension (6 papers, 2014 to 2026). The presence of chronic increased pressure in the systemic arterial system. "Polymorphisms in SLC24A3 have been associated with salt-sensitive vasoconstriction and hypertension, while the expression of NCKX3 protein was linked to preeclampsia (i.e., pregnancy complicated by high blood pressure))." (PMID 29043008, 2017). "Among those, CMTM5, ITGA2B, and SLC24A3 are implicated in platelet function and cardiovascular complications, whereas ENOSF1 has been previously linked to hypertension." (PMID 41500120, 2026). "For example, SLC24A3, a previously reported high blood pressure-related gene, was increased in nine cell types (e.g., CM, fibroblast, and EC)." (PMID 37084237, 2023). "In GWAS analysis, the genes CYP3A5, SLC24A3 and CTSA are observed in obesity related diseases like Hypertensive disease, Asthma, Coronary Artery Disease, Essential Hypertension, Hypertensive disease and Heart failure." (PMID 32027667, 2020).
breast carcinoma (5 papers, 2019 to 2025). "Knockdown of expression of transcription factor TFAP2C in hormone responsive breast carcinoma cells resulted in deregulation of a number of target genes including SLC24A3, which was downregulated." (PMID 31083655, 2019). "Notably, one of the comorbidities with significant associated pathways, breast cancer, contained SNPs affecting Solute Carrier Family 4 Member 7 (SLC4A7) and Solute Carrier Family 24 Member 3 (SLC24A3) genes." (PMID 33924631, 2021).
colon cancer (2 papers, 2017 to 2023). "Previous studies have illustrated that SLC24A3 was significantly differentially expressed in colon cancer, ovarian cancer, and cervical cancer compared with normal control tissues." (PMID 36798148, 2023).
fibromyalgia (2 papers, 2019 to 2023). A chronic disorder of unknown etiology characterized by pain, stiffness, and tenderness in the muscles of neck, shoulders, back, hips, arms, and legs. "Several genes/loci have been reported more than once in CWP, fibromyalgia, and MCP, including EXD3, SLC39A8, AMIGO3/GMPPB/RNF123, C6orf106, FAF1, SLC24A3, and LINC01065/LINC00558." (PMID 37144689, 2023).
Obesity (2 papers, 2012 to 2020). Accumulation of substantial excess body fat. "We also observe previously identified obesity associated genes, such as Zfp69, Slc24a3, Qpctl, Atp10a, and Folr2." (PMID 22471599, 2012). "This suggests that the effect of the obesity risk associated with Qpctl andCrhr1 are mediated by Slc24a3's effect on the levels of glucose in the bloodstream." (PMID 22471599, 2012). "SLC24A3 and WNK1 are mapped to traits like fat body mass and body mass index which are closely associated with obesity." (PMID 32027667, 2020).
cervical cancer (1 paper, 2023). A primary or metastatic malignant neoplasm involving the cervix. "Moreover, experiments to illustrate the underlying function and mechanism of SLC24A3 in the therapy of cervical cancer pain were not performed yet." (PMID 36798148, 2023).
cervical squamous cell carcinoma (1 paper, 2023). A squamous cell carcinoma arising from the cervical epithelium. "Nevertheless, the prognostic value of SLC24A3 expression with cervical squamous cell carcinoma and endocervical adenocarcinoma (CESC) patients remains uncertain." (PMID 36798148, 2023).
colorectal cancer (1 paper, 2024). A primary or metastatic malignant neoplasm that affects the colon or rectum. "Finally, colorectal cancer cells migration, growth and colony formation assays were performed in RKO cells with the overexpression or knockdown SLC8A3, SLC24A2, SLC24A3, or SLC24A4." (PMID 39006025, 2024).
disorders of the lens (1 paper, 2021). "Most were associated with disorders of the lens, with the strongest association observed for the intronic variant rs4814857 at SLC24A3 (P = 2.48 × 10−39)." (PMID 34127677, 2021).
endometrial cancer (1 paper, 2021). Primary or metastatic malignant neoplasm involving the endometrium (mucous membrane that lines the endometrial cavity). "The LASSO regression model and survival analysis further suggested that two hub genes (PAMR1 and SLC24A3) could serve as potential biomarkers for the treatment or diagnosis of cervical and endometrial cancers." (PMID 34834529, 2021).
glioblastoma (1 paper, 2024). The most malignant astrocytic tumor (WHO grade IV). "While considering glioblastoma, we found SOX2, DUSP6, SLC24A3, KCNIP3, and DPP4 to be differentially the most upregulated, which have previously been found to be effective in glioblastoma formation and prognosis." (PMID 38769480, 2024).
gynecologic cancer (1 paper, 2021). "The results demonstrated that PAMR1 and SLC24A3 may serve as potential prognostic biomarkers in gynecologic cancer." (PMID 34834529, 2021). "Moreover, using GEPIA2, the expression of PAMR1 and SLC24A3 in tumor tissues was downregulated significantly compared with the normal tissue and was related to the OS of patients with gynecologic cancer." (PMID 34834529, 2021). "Finally, the results suggested that PAMR1 and SLC24A3 may act as prognostic biomarkers for gynecologic cancer in our study." (PMID 34834529, 2021).
nasopharyngeal carcinoma (1 paper, 2019). A carcinoma arising from the nasopharyngeal epithelium. "In tumorspheres of EBV positive nasopharyngeal carcinoma cells, SLC24A3 was one of several CSC markers that were upregulated compared to corresponding monolayer cells." (PMID 31083655, 2019).
pancreatic cancer (1 paper, 2023). "Hence, we were unable to understand how SLC24A3 exerted its function in pancreatic cancer during occurrence and development." (PMID 36798148, 2023). "It was noteworthy that SLC24A3 mRNA was significantly higher expressed in PANC-1 and serves as human pancreatic cancer cell lines, compared with HUCEC cell lines." (PMID 36798148, 2023). "As far as we know, however, no previous research has investigated whether SLC24A3 is involved in occurrence and development of pancreatic cancer." (PMID 36798148, 2023).
Stroke (1 paper, 2020). Sudden impairment of blood flow to a part of the brain due to occlusion or rupture of an artery to the brain. "We identified colocalization signals at several established single trait loci such as TCF21, ADAMTS7, and LIPA for CAD, and NGF, FHL5, TSPAN2, and SLC24A3 for stroke." (PMID 31917787, 2020).
tumor (10 papers, 2019 to 2026). "The results demonstrated that downregulation of SLC24A3 in tumor tissues was greatly associated with better overall survival (log rank p = 0.0019), disease-free survival (log rank p = 0.049), and progression-free survival (log rank p = 0.049) among patients with CESC." (PMID 36798148, 2023). "Our study established a novel six‐gene (APOC1, GLTP, ISG20, SPP1, SLC24A3 and UPP1) signature that was closely associated with the immune response and tumour immune microenvironment." (PMID 34498424, 2021). "Our study established a novel six‐gene (APOC1, GLTP, ISG20, SPP1, SLC24A3 and UPP1) signature that was closely associated with the immune response and the tumour immune microenvironment." (PMID 34498424, 2021). "The boxplot demonstrated that mRNA expression levels of PAMR1 and SLC24A3 were significantly lower in tumor tissues than in normal samples (p < 0.05)." (PMID 34834529, 2021). "Patients with M0 stage tumors showed only CACNA1H, SLC24A3 and NALCN associated with OS differences, while ATP2A1, ATP13A2, TRPC1, and NALCN proved to be significantly associated with OS in the N1–N3 tumor stage patient subgroup." (PMID 31083561, 2019). "This evidence suggested a significant correlation between SLC24A3 and tumor-immune infiltration." (PMID 36798148, 2023). "Notably, we established a novel six‐gene (APOC1, GLTP, ISG20, SPP1, SLC24A3 and UPP1) prognostic signature and discovered for the first time that this signature was associated not only with intrinsic aggressive features but also with the tumour immune microenvironment." (PMID 34498424, 2021). "As illustrated in box plot, SLC24A3 expression in tumor groups was all considerably lower than nontumor groups in TCGA-CESC and GSE63514 cohorts (all p < 0.05)." (PMID 36798148, 2023). "This study manifested that SLC24A3 had a considerable difference of expression in tumor and normal tissues of CESC, and we also proved that low-expressed SLC24A3 has well survival rates in patients with CESC." (PMID 36798148, 2023). "Among them, the expression of PAMR1 and SLC24A3 in tumor tissues was downregulated significantly compared to the normal tissue, and found to be statistically significant in survival rates between the CC and EC of patients (p < 0.05)." (PMID 34834529, 2021). "Tumor samples of Inserm series were predicted in 2 and 4 subtypes molecular classification using a predictor based on nine genes: ADAM19, ETS1, and PDCD1LG2 for C1 and C2; CLDN1, DSC3, and SLC24A3 for C1A and C1B; CHL1, ECM2, and PTPN13 for C2A and C2B subtype prediction." (PMID 32083805, 2020).
cancer (7 papers, 2022 to 2024). A tumor composed of atypical neoplastic, often pleomorphic cells that invade other tissues. "This introduces a promising direction for our subsequent research, for the propose of further elucidating and understanding the mechanism of SLC24A3 in relieving cancer pain." (PMID 36798148, 2023). "The expression of PAMR1 and SLC24A3 in cancer tissue is downregulated significantly compared to normal tissue." (PMID 38248716, 2023). "Based on the available research results, we have reason to believe that upregulating the expression of SLC24A3 will effectively alleviate the cancer pain in CESC." (PMID 36798148, 2023). "This suggested that SLC24A3 was differentially expressed in different cancer type compared with normal control tissues." (PMID 36798148, 2023). "Additionally, we programmed a series of analyses, including genomic profiling, enrichment analysis, immune infiltration analysis, and therapy-related analysis to identify the mechanism of the SLC24A3 in the process of cancer in CESC." (PMID 36798148, 2023). "Therefore, in this essay, we explore a new biomarker SLC24A3, which has functions not only in prognostic as well as treatment but also in relief cancer pain of patients with CESC." (PMID 36798148, 2023). "In other words, cancer pain is triggered precisely because SLC24A3 is low expressed in CESC, which may be due to the alteration of inflammation-related immune mechanisms." (PMID 36798148, 2023). "Given that SLC6A4 was highly associated with pain regulation and SLC24A3 has positively correlation with SLC6A4, we hypothesized that SLC24A3 was associated with cancer pain in CESC." (PMID 36798148, 2023). "Verifying whether SLC24A3 is appropriate as a biological indicator in early diagnosis, evaluation of prognosis and relief cancer pain of CESC patients is extremely essential." (PMID 36798148, 2023). "The association of SLC8A3, SLC24A2, SLC24A3 and SLC24A4 with cancer is still unknown." (PMID 39006025, 2024). "For instance, genes like SLC24A3, GALM, MPO, and ATP1B1 appear to be commonly down-regulated across various solid cancers, while other MRGs are frequently up-regulated in many cancer types." (PMID 38995414, 2024).
SLC24A3 also shares sentences with these, for which no sentence is quoted: Arrhythmia (3 papers); colitis (3); diabetes (3); heart failure (3); asthma (2); Cerebral ischemia (2); Hyponatraemia (2); Ventricular arrhythmia (2); Age-related cataract (1); Alzheimer disease (1); brain aneurysm (1); Cardiac Arrhythmias (1); cardiomyopathies (1); cardiovascular diseases (1); congenital stationary night blindness (1); Coronary Artery Disease (1); depression (1); Duchenne muscular dystrophy (1); endocervical adenocarcinoma (1); essential hypertension (1); familial hemiplegic migraine (1); heart disease (1); Hematochezia (1); Hypercalcemia (1); hyperthyroidism (1); infection (1); inflammatory bowel disease (1); ischemia (1); meningioma (1); myocardial infarction (1).
A further 5 diseases each share a sentence with SLC24A3 in 1 paper.